BCR (BCR activator of RhoGEF and GTPase)
Diseases named in the same sentence as BCR in open-access papers (continued):
Sharing a sentence is not in itself a finding about the gene and the disease.
breast cancer (26 papers, 2008 to 2025). A primary or metastatic malignant neoplasm involving the breast. "Interestingly, combined PI3K and PARP inhibition have also provided more efficient responses in BRCA1-deficient breast cancer cells and dual ATR and BCR inhibition has also been proven to be synergistic in ATM-defective CLL cells." (PMID 31974435, 2020). "For breast cancer (BRCA), PAM50 and TNBC patient cohorts are retrieved from their original publications and metastasis data is retrieved from BCR Biotab." (PMID 38254834, 2024). "Previous studies indicated that AP-1 is involved in BCR-mediated and TGF-β-induced Blimp-1 gene expression in B lymphocytes and breast cancer cells, respectively." (PMID 35185556, 2022). "Initial approaches were candidate-based, such as the use of imatinib (Gleevec) for acute myeloid leukemias harboring BCR-ABL gene translocations, HER2Neu positive breast cancer treatment with trastuzumab (Herceptin), and, prior to this, tamoxifen in ER/PR positive breast cancer patients." (PMID 24637659, 2014). "Most biological functions in the MCF7 network are controlled by the PIK3R1 gene, and many other pathways, including apoptosis, ErbB, JAK–STAT, HIF-1, the control of the actin cytoskeleton, TNF, cancer-related pathways, TCR, BCR, and TLR signaling pathways, may also be related to breast cancer." (PMID 36675976, 2022). "Other genes, including ATP5A, BCR, FGFR4, PDPK1, PIP5K1C, RIOK3, and SRC, also act to regulate TRAIL-induced apoptosis, but their potential to overcome resistance to TRAIL-induced cytotoxicity when inhibited may be more context specific (that is, in a more-restricted subset of breast cancer cells)." (PMID 24745479, 2014). "For example, the mammary tumors in MMTV- c-Neu mice do not respond to L-744,832, but the pre-B-cell leukemia in BCR/Abl transgenic mice regressed upon treatment with SCH66336." (PMID 18489761, 2008). "However, the BCR-ABL and PDGF pathways inhibited by gleevec is down-regulated in metastasizing tumors according to our analysis, which might indicate that inhibition of ABL is not relevant for treatment of breast cancer." (PMID 19116006, 2008).
myeloid leukemia (26 papers, 2009 to 2025). A clonal proliferation of myeloid cells and their precursors in the bone marrow, peripheral blood, and spleen. "Recently, via homologous recombination (HR) using CRISPR/Cas9 system, we introduced T315I gatekeeper mutation into the intrinsic BCR::ABL1 fusion gene in human Ph + myeloid leukemia cell lines and Ph + lymphoid leukemia cell line." (PMID 40208408, 2025). "In the present study, we successfully introduced F311I, T315I, and F311I/T315I mutations into the intrinsic BCR::ABL1 gene of TCCS (a TKI-sensitive human Ph+ myeloid leukemia cell line) using the CRISPR/Cas9 system." (PMID 39872583, 2024). "The presence of both p40ABL/BCR and p96ABL/BCR induced a myeloid leukemia-like phenotype with maturation, associated with moderate splenomegaly (0.2–0.6 mg spleen weight)." (PMID 19876398, 2009). "Furthermore, aucubin inhibited the phosphorylation and expression of the BCR-ABL protein in human myeloid leukemia cells, where BCR-ABL encoded tyrosine kinases—i.e., an enzyme playing an essential role in many cell functions, e.g., signaling and cell growth." (PMID 37241895, 2023). "In the present study, to verify the utility of the CBE system, we first tried to introduce the T315I (ACT to ATT) mutation of the BCR::ABL1 fusion gene, which is the most important BCR::ABL1 mutation, in a human Ph+ myeloid leukemia cell line." (PMID 40342439, 2025). "Fundamental oncogenic properties of BCR::ABL1 in Ph + lymphoid leukemia cells must be identical to those in Ph + myeloid leukemia cells." (PMID 40208408, 2025). "Sca1-directed expression of human BCR-ABLp210 within HSCs/HPCs in the transgenic mice (Sca1-BCR-ABLp210) resulted in a myeloid leukemia." (PMID 35563454, 2022). "This suggests that DAC can also promote the apoptosis of myeloid leukemia cells by downregulating the expression of BCR-ABL." (PMID 33532040, 2021). "In contrast to BCR-ABLp190, transient expression of BCR-ABLp210 restricted to the HSPC compartment of mice led to mature myeloid leukaemia." (PMID 32213936, 2020). "To test if Msi2-reporter activity can effectively identify LSCs and therapy resistance in myeloid leukemia, we used a BCR-ABL/NUP98-HOXA9-driven model of bcCML21." (PMID 33243988, 2020). "Transient expression of BCR-ABLp210 in HSPCs was sufficient to promote myeloid leukemia, and Imatinib treatment leads to downregulation of Dnmt1 but does not eradicate the disease." (PMID 29955131, 2019). "We selected patients claiming reimbursement for tyrosine kinase inhibitors (TKI) or with hospital discharge diagnoses for CML, BCR/ABL‐positive or with full reimbursement of health care expenses for myeloid leukemia." (PMID 31038849, 2019). "In support of this notion, we have previously shown that the transient expression of BCR-ABLp210 restricted to the hematopoietic stem/progenitor cell (HSPC) compartment of mice is capable of inducing mature myeloid leukemia." (PMID 29955131, 2019). "Several reports indicated that SFKs played an important role in the pathogenesis of BCR/ABL+ myelogenous leukemia." (PMID 29312576, 2017). "The fusion protein PML-RARA is associated exclusively with myeloid leukemia in both humans and mice (unlike BCR-ABL and MLL fusion proteins, which can lead to myeloid or lymphoid leukemias)." (PMID 23056333, 2012). "Furthermore, co-expression of kinase-defective HCK mutants with BCR/ABL strongly impaired transformation of cytokine-independent growth of myeloid leukemia cells, while treatment with the broad-spectrum SFK inhibitor PP2 abrogated BCR/ABL-dependent activation of STAT5A." (PMID 26087188, 2015). "These processes are dominant over the BCR-ABL induced nuclear accumulation of STAT5A and therefore give a rational explanation for the cytoplasmic localization of STAT5A in a number of myeloid leukemias." (PMID 25885255, 2015).
myeloid leukemia (continued). "Regarding diagnostic considerations, although the bone marrow biopsy indicated neutrophilia, the absence of CML-specific karyotypes and BCR-ABL fusion gene excluded the diagnosis of myeloid leukemia." (PMID 40761243, 2025). "The BCR-ABLp210 occurs in patients with CML, and in acute lymphoid and myeloid leukaemias." (PMID 32213936, 2020). "Moreover, Hck is frequently overexpressed in myeloid leukemias and links STAT5 to BCR-ABL signaling." (PMID 25885255, 2015). "Comparable selection for host cells expressing low levels of phosphorylated STAT5 has been reported in a BCR-ABL mouse model to permit a selective advantage for BCR-ABL expressing pro-B cells but not myeloid leukemia cells over aged progenitors with declining competitive repopulating ability." (PMID 26338970, 2015). "However, in the whole transcriptome, the gene expression profile of Ph-positive myeloid leukemia cell lines and that of CML patients’ samples were substantially different from that of p210 or p190 BCR::ABL1 sublines and parental cells, regardless of whether cultured with GM-CSF or not." (PMID 35999358, 2023).
B-cell lymphoma (22 papers, 2008 to 2025). "While the advanced B-cell lymphomas often depend on mutations of BCR or members of its down-stream signaling pathways, T-cell lymphomas tend to develop activating mutations of selected JAKs and STATs, normally activated by cytokines critical for T-cell development and function." (PMID 38638855, 2024). "In addition to ROR1, other aberrantly expressed cell-surface receptors may play a pathogenic role in B-cell lymphomas by at least partially substituting for BCR-generated cell signaling." (PMID 38638855, 2024). "We first used PCR-based strategies to compare the Pten exomes of these T-LBL cells to both normal mouse splenocytes and to ATMKO B cell lymphomas found to be dependent on BCR/NF-kB signaling." (PMID 39637056, 2024). "Mutations affecting the binding site of HVEM interaction with BTLA in cis promotes B cell lymphoma development because of unleashed BCR signaling and dysregulation of B cell activation and further differentiation." (PMID 37033927, 2023). "Carabin has also been demonstrated to be a negative regulator in B-cell activation in SLE and B-cell lymphoma through inhibiting crosstalk between BCR and TLR9 pathways." (PMID 35265067, 2022). "Recent evidence has highlighted the involvement of the BCR signaling in mitigating GSK-3 activity in some B-cell NHLs." (PMID 35681507, 2022). "Carabin has also been reported to be a novel negative regulator of B-cell function in systemic lupus erythematosus (SLE) and B-cell lymphoma through inhibiting the crosstalk between BCR and TLR9 pathways." (PMID 35265067, 2022). "One of the most important signaling molecules for malignant B-cell proliferation, survival, and drug-resistance is the BCR whose activity is aberrantly regulated in many patients with B-cell NHLs due to multiple reasons." (PMID 35681507, 2022). "Of note, at least in certain B cell lymphomas, the BcR IG genes are intraclonally diversified, likely in a context of ongoing interactions with antigen(s)." (PMID 32083012, 2020). "The clonotypic B cell receptor immunoglobulin (BcR IG) plays a seminal role in B cell lymphoma development and evolution." (PMID 32083012, 2020). "Overall, delving into the BcR IG gene sequences emerges as key to understanding B cell lymphoma pathophysiology, refining prognostication and assisting in making educated treatment choices." (PMID 32083012, 2020). "Except for BCP-1 and CI-1, cell lines derived from unspecified B cell lymphoma (n = 4) also express high level of heavy and light chain BCR rearrangements." (PMID 30285677, 2018). "Btk, a component of the BCR pathway, is considered a potential novel target for the treatment of B cell lymphoma, and the Btk inhibitor, ibrutinib, has been successfully applied in clinical trials." (PMID 28036258, 2017). "Remarkably, doxycycline inhibited growth of all tested DLBCL cells, including cells that are resistant to several currently-tested inhibitors that target HSP90 or the upstream regulators of the BCR signaling pathway in B-cell lymphomas." (PMID 26142707, 2015). "BTK kinase occupies an important position in BCR signaling, and theoretically, due to the mimicry of BCR signaling by LMP2A, the combined use of BTKi may be effective in treating EBV‐associated B‐cell lymphoma." (PMID 39866943, 2025). "Additionally, the role of BCR in recognizing antigens and initiating signaling pathways makes it a central player in the development of B‐cell lymphomas, as chronic BCR stimulation can lead to aberrant B‐cell proliferation." (PMID 37929016, 2023). "Moreover, BcR IG gene repertoire profiling suggests that unique immune pathways lead to distinct B cell lymphomas through targeting cells at different stages in the B cell differentiation trajectory (e.g., germinal center B cells in follicular lymphoma, FL)." (PMID 32083012, 2020).
B-cell lymphoma (continued). "Indeed, BcR IG gene repertoire biases have been documented in different B cell lymphoma subtypes, alluding to selection of B cell progenitors that express particular BcR IG." (PMID 32083012, 2020). "Similarly, many B‐cell lymphomas, including Burkitt lymphoma (BL), require continuous BCR signaling for their tumor growth." (PMID 29669863, 2018). "The Id-peptide pA20-36 is a specific binder for the surface Ig-BCR of A20 B-cell lymphoma cells." (PMID 25983658, 2015). "We suggest that FTIs may be able to block the proliferation of BCR-expressing B cell lymphomas by interfering with the antigen receptor and/or cytokine signaling pathways within the transformed cells." (PMID 18489761, 2008). "Therefore, the BCR signaling network has become an attractive target in the therapy of B-cell NHLs." (PMID 35681507, 2022). "MiR 17-92 cluster is amplified in high-grade B-cell lymphoma with Burkitt lymphoma signature, resulting in higher expression of miR17-92 and lower expression of BIM and PTEN and increased BCR signaling." (PMID 29641489, 2018). "It was observed that, in c-Myc-driven mouse B-cell lymphomas and human Burkitt lymphoma cells, genetic ablation of BCR does not, per se, preclude the growth of neoplastic cells." (PMID 35681507, 2022). "To study the role of the BCR complex in supporting the growth of B‐cell lymphomas, we used the CRISPR/Cas9 gene‐editing tool to generate Ramos B‐cell mutants lacking all (BCR‐null) or some of the four BCR components, H and L chains, Igα and Igβ." (PMID 29669863, 2018).
prostate carcinoma (22 papers, 2008 to 2024). A carcinoma that arises from epithelial cells of the prostate gland. "In the latest published study on biomarkers of prostate cancer, hub genes such as KIF20A and CDCA8 are associated with adverse BCR-free survival of PCa patients and have better specificity and sensitivity in the diagnosis of prostate cancer." (PMID 31565099, 2019). "BCR is often associated with the presence of more aggressive prostate cancer and early detection of biochemical recurrence in men with prostate cancer undergoing definitive therapy may help identify patients who would benefit from adjuvant or neo-adjuvant therapies." (PMID 29158516, 2017). "Transcriptomic overexpression of connective tissue genes correlated to worse clinical features, such as ECE, clinically significant cancer and BCR, identifying the potential prognostic value of the gene signature of the connective tissue in prostate cancer." (PMID 37108678, 2023). "BCR+ and BCR− patients were identified and selected from a retrospective group of prostate cancer patients who had previously undergone definitive therapy and for whom the outcomes had been recorded, all under the auspices of an IRB approved study." (PMID 29158516, 2017). "The goal of the study was to evaluate and study shape differences of the prostate capsule as observed in atlases between BCR+ and BCR− prostate cancer patients." (PMID 29158516, 2017). "Statistically significant differences in the shape of the prostate capsules were observed between BCR+ and BCR− prostate cancer patients, mostly localized close to the posterior part of the prostate." (PMID 29158516, 2017). "Thus we adopt an atlas based statistical comparison approach to identify regions on the prostate that are affected and are different between BCR+ and BCR− prostate cancer patients." (PMID 29158516, 2017). "Clinical studies also support that HMGB1 is overexpressed in PCa patients and may serve as a novel prognostic marker for BCR-free survival for prostate cancer patients after undergoing radical prostatectomy." (PMID 23766911, 2013). "Notably, all seven proteins were significantly associated with progression in Prostate Cancer Transcriptome Atles (PCTA) and NPM1NPM1, UQCRH, and VCAN were further validated in The Cancer Genome Atlas (TCGA), where they were upregulated in BCR+/BCR-." (PMID 35954429, 2022). "It is well understood that driver gene fusions are typically found to be recurrent, such as BCR-ABL, ETV6-NTRK3, and TMPRSS2-ERG in prostate cancer, and consequently they are ideal targets for therapeutic intervention." (PMID 22032724, 2011). "An included study provided the first evidence that the prevalence of PD-L1 expression is very common in primary prostate cancer and is a negative predictor for BCR-free survival." (PMID 30733677, 2018). "In this work we explored if an atlas-based comparison approach reveals shape differences in the prostate capsule as observed on pre-treatment T2-weighted MRI between prostate cancer patients who do (BCR+) and do not (BCR−) have BCR following definitive therapy." (PMID 29158516, 2017). "The rearrangements of UBAP2L and EHMT1 have been reported in liver, lung, breast, ovary, and prostate cancer but not in hematological malignancies, and ABL1 or BCR has not been reported as their partner genes." (PMID 39596557, 2024).
diffuse large B-cell lymphoma (21 papers, 2013 to 2025). "Activated B‐cell‐like diffuse large B‐cell lymphomas (ABC‐DLBCL) carry mutations of the BCR and its signal components, resulting in chronic active NFκB signaling and increased tumor survival." (PMID 29669863, 2018). "Research using tumour organoids has revealed that the B‐cell receptor (BCR) signalling pathway plays a pivotal role in the progression of diffuse large B‐cell lymphoma (DLBCL)." (PMID 40538372, 2025). "CXCR4 signaling has been proposed as an acquired resistance mechanism in BCR-dependent diffuse large B-cell lymphomas." (PMID 37629071, 2023). "The BCR is also able to induce the IL-10/STAT3 signaling with increased expression of PD-L1 in diffuse large B-cell lymphoma." (PMID 31382969, 2019). "Still, as part of the CARD11-containing CBM-1 complex, BCL10 is an essential factor for survival of the activated B cell type of diffuse large B cell lymphoma (ABC DLBCL) that are addicted to chronic BCR signaling." (PMID 30022982, 2018). "In activated B-cell type diffuse large B-cell lymphoma (ABC-DLBCL), activating mutations in B-cell receptor subunits are present in approximately 23% of cases and result in constitutive BCR-driven CBM-dependent NF-κB activity." (PMID 30158935, 2018). "The human activated B-cell like diffuse large B-cell lymphoma (ABC-DLBCL) cells are characterized by chronic active BCR signaling." (PMID 29953499, 2018). "Interestingly, Ccl4 was already identified as a candidate for biomarker for BCR pathway activation and prognostic in diffuse large B cell lymphoma and as an inflammation-related diseases biomarker (Olink proteomics)." (PMID 32659965, 2020). "Fluorescent in situ hybridization study using BCR/ABL probe dual probe as a means to assess ploidy in specific morphologic areas of the tumor showed the majority of cells in diffuse large B-cell lymphoma area to have 4 ABL signals for chromosome 9 (red) and 4 BCR signals for chromosome 22 (green)." (PMID 23738160, 2013). "In diffuse large B-cell lymphoma, CDK12 activated MYC to inhibit miR-28-5p/EZH2 and amplify BCR signaling to promote its progression." (PMID 36463205, 2022). "This supports the notion of intertwined signaling pathways in germinal center B‐cell‐like‐subtype diffuse large B‐cell lymphoma involving stimulation of CD20 and BCR on the cellular path toward programmed cell death and reduction of CD20 levels." (PMID 32585766, 2020). "As previously reported, TLR9, in combination with BCR as well as mutant isoforms of MYD88, could result in sustained activity of NF-κB in the activated B-cell-like subtype of diffuse large B-cell lymphoma." (PMID 35707851, 2022). "BCR-mediated cell signaling in the absence of identifiable antigenic ligand gained most attention in the context of diffuse large B-cell lymphoma (DLBCL)." (PMID 38638855, 2024).